NLRP3 (NLR family pyrin domain containing 3)
Diseases named in the same sentence as NLRP3 in open-access papers (continued):
Sharing a sentence is not in itself a finding about the gene and the disease.
renal fibrosis (140 papers, 2013 to 2026). A final common manifestation of a wide variety of chronic kidney diseases characterized by glomerulosclerosis and tubulointerstitial fibrosis. "Pathological assessments further revealed ameliorated renal fibrosis and preserved mitochondrial ultrastructure in NLRP3-deficient mice." (PMID 42196240, 2026). "Hirudin reduced inflammation and renal fibrosis, and this effect was associated with ferroptosis regulated by NLRP3." (PMID 40298655, 2025). "Hydroxy saffron yellow pigment A can inhibit the expression of NLRP3 inflammatory vesicle‐associated proteins through downregulation of LPS, etc., inhibit the activation of NLRP3 inflammatory vesicles, and attenuate renal fibrosis." (PMID 41245191, 2025). "The in-vivo results verified that the therapeutic effect of hirudin on renal fibrosis was probably linked to the inhibition of ferroptosis via the STAT3/NLRP3 signaling pathway." (PMID 40298655, 2025). "In some studies, AP inhibits the NOD-like receptor thermal protein domain associated protein 3 (NLRP3)/NF-κB inflammasome activation by lowering uric acid and decreasing renal fibrosis." (PMID 38570748, 2024). "BSHX significantly reduced renal fibrosis and pyroptosis, and its mechanism was mainly associated with the inhibition of reactive oxygen species (ROS)/NLRP3-mediated inflammasome activation." (PMID 38785272, 2024). "Here we present the first evidence that IL11 drives activation of the ASC/NLRP3 inflammasomes, causing villus pyroptosis, placental and renal fibrosis, and the maternal syndrome of preeclampsia, including chronic post-natal hypertension, in mice." (PMID 37292200, 2023). "In renal cells induced by HG, DHQ significantly inhibits the activation of NLRP3 inflammasomes and renal fibrosis-associated proteins, reducing cell proliferation and oxidative stress." (PMID 37215100, 2023). "With more profound research, the activation of NLRP3 inflammasome has been implicated in the progression of renal fibrosis, all of which interact with complicated metabolic alterations in the kidneys." (PMID 37500614, 2023). "It is reported that RIPK3 is associated with renal fibrosis in DKD by activating NLRP3 inflammasome." (PMID 37215100, 2023). "Other studies have reported that the NLRP3 inflammasome is associated with myofibroblast differentiation during renal fibrosis." (PMID 36271349, 2022). "It is reported that RIPK3 inhibition or RIPK3 deficiency attenuates renal fibrosis via the regulation of the NLRP3 inflammasome in a mouse model of FA nephropathy." (PMID 35924048, 2022). "Our previous study demonstrated that Nlrp3 deficiency attenuated mitochondrial dysfunction and renal fibrosis in a model of unilateral ureteral obstruction (UUO)." (PMID 33628380, 2021). "Our previous study also showed that Nlrp3 deficiency attenuated renal fibrosis in a mouse unilateral ureteral obstruction model of CKD." (PMID 33628380, 2021). "And their research findings demonstrate a novel function for Huaier in the regulation of NLRP3 inflammasome activation and suggest a potential role for Huaier in NLRP3 inflammasome-associated diseases such as renal fibrosis." (PMID 32655761, 2020). "A previous work in unilateral ureteral obstruction mice showed that the inflammation and renal fibrosis were associated with Nlrp3 inflammasome activation and the downstream proinflammatory cytokines production." (PMID 28097088, 2017). "(2023) they observed a significant increase in the expression levels of BNIP3 and HIF-1 α in UUO mice and a hypoxia-induced HK-2 cell model, as well as a significant up-regulation of TGF-β1 and α-SMA associated with renal fibrosis, accompanied by the activation of the NLRP3 inflammasome." (PMID 38680884, 2024). "Our results show that NLRP3 activation was associated with renal fibrosis." (PMID 37685978, 2023). "Recently, mROS was confirmed related to the CKD, and silencing the NLRP3 gene could alleviate the associated mitochondrial dysfunction and renal fibrosis." (PMID 35382689, 2022).
renal fibrosis (continued). "Furthermore, it was shown in another study of adenine-induced renal fibrosis that treating mice with an inhibitor of NLRP3 activation, as well as employing NLRP3-deficient mice, reduced fibrosis." (PMID 35409312, 2022). "Additionally, the NLRP3 inflammasome is associated with pyroptosis, a process that is also involved in renal fibrosis." (PMID 32039201, 2019). "Thus, in the context of progressive tubular atrophy and increased renal fibrosis, a loss of NLRP3 expression in advancing IgAN becomes plausible." (PMID 27093923, 2016). "Finally, we evaluated whether Nlrp3 deficiency affects renal fibrosis following UUO by analyzing the accumulation of myofibroblasts, total collagen deposition and renal concentrations of the profibrotic molecule Transforming Growth Factor-β (TGF-β)." (PMID 24454932, 2014). "In conclusion, macrophage NLRP3 is profibrotic and mediates renal fibrosis via the TGF-β/Smad3-MMT mechanism." (PMID 42157945, 2026). "illustrated pterostilbene’s ability to trigger autophagy in a murine model of urate nephropathy, leading to the inhibition of TGF-β-induced NLRP3 inflammasome activation and epithelial-mesenchymal transition, consequently impeding renal fibrosis progression." (PMID 40841164, 2025). "Compared to the model group, BBR significantly reduced NLRP3 levels in renal fibrosis animals (Sample size: 52; SMD = −2.77 (95% CI: −3.57 to −1.97), P = 0.241; χ2 = 2.84, I2 = 29.6%)." (PMID 40567371, 2025). "In a lipopolysaccharide-induced HK-2 cells fibrosis model, PNS attenuated renal fibrosis by suppressing NLRP3 inflammasome activation and cellular pyroptosis." (PMID 40841164, 2025). "Conversely, TGF-β treatment of TECs from NLPR3−/− mice results in reduced Smad2/3 phosphorylation and diminished α-SMA/MMP9 expression, confirming that NLRP3 facilitates TEC-driven renal fibrosis via the TGF-β/Smad pathway." (PMID 41357229, 2025). "A previous study of a UUO‐induced renal fibrosis model revealed that circACTR2 activates the NLRP3 inflammasome, leading to macrophage apoptosis and the release of inflammatory factors by sponging miR‐561." (PMID 39799463, 2025). "Lactylation exacerbates renal fibrosis via NLRP3 inflammasome activation, as previously discussed in Section 2.2.2." (PMID 41393289, 2025). "Emerging research underscores the dual role of the NLRP3 inflammasome in driving both inflammation and renal fibrosis, pivotal mechanisms in DN progression." (PMID 40458807, 2025). "Our published research invested that inhibition of the NLRP3 inflammasome was confirmed to reduce renal fibrosis in DN rats." (PMID 40458807, 2025). "Extracellular calcium initiates signal transduction via the calcium-sensing receptor, effectively activating the NLRP3 inflammasome and inducing renal fibrosis." (PMID 41357229, 2025). "Inhibit inflammation activation mediated by ROS and NLRP3 to prevent renal fibrosis and cellular death." (PMID 40841164, 2025). "More relevantly, Tan IIA treatment failed to inhibit the expression of fibrotic factors, highlighting that the function of Tan IIA in regulating NRF2/NLRP3 for treating UA-induced renal fibrosis depends on NRF2 activation." (PMID 39473254, 2025). "Studies have shown that the activation of the NLRP3 inflammasome can trigger apoptosis and renal fibrosis, and by inhibiting the activation of the NLRP3 inflammasome, the process of fibrosis in mice can be effectively slowed down." (PMID 41394140, 2025). "Its activation in podocytes not only exacerbates glomerular inflammation but also promotes advanced glomerulosclerosis, establishing NLRP3 as a key inducer of renal fibrosis." (PMID 41357229, 2025). "In an adenine-induced model of CKD, butyrate has been shown to attenuate renal fibrosis by suppressing activation of the NLRP3/STING/NF-κB signaling pathway." (PMID 41048436, 2025). "In renal fibrosis research, Psoralen showed therapeutic effects by inhibiting NLRP3 inflammasome activation." (PMID 40038816, 2025).
renal fibrosis (continued). "Knockout of the NLRP3 gene preserves mitochondrial morphology in mouse renal tubules, ameliorates CKD-associated hypertension and proteinuria, and mitigates renal fibrosis." (PMID 41357229, 2025). "By activating the NLRP3 inflammasome, previous studies have suggested that Ang II plays a role in the pathological process of renal fibrosis." (PMID 40841164, 2025). "This study demonstrated that hirudin effectively treats renal fibrosis by regulating ferroptosis through the STAT3/NLRP3 signaling pathway." (PMID 40298655, 2025). "This study demonstrates that the combination of ultrasound and microbubble therapy can potentiate the inhibitory effect of 5 mg/kg MCC950 on the NLRP3 inflammasome, thereby improving renal function and mitigating renal fibrosis in CKD rats." (PMID 40822454, 2025). "In summary, the NLRP3 inflammasome mediates renal fibrosis through oxidative stress and inflammatory pathways." (PMID 41357229, 2025). "Clinically, peripheral blood mononuclear cells from IgA nephropathy patients exhibit elevated NLRP3 mRNA expression, which correlates positively with renal fibrosis indices." (PMID 41357229, 2025). "Treatment with the STAT3 activator colivelin reversed this effect, further verifying that hirudin inhibits ferroptosis by regulating the STAT3/NLRP3 signaling pathway in renal fibrosis." (PMID 40298655, 2025). "Based on these findings, there is a complex interaction among ROS, NLRP3 inflammasome, and autophagy in the development of renal fibrosis." (PMID 37498374, 2024). "An activated NLRP3 inflammasome contributes to unilateral ureteral obstruction (UUO)-induced renal fibrosis, while gemigliptin has a renoprotective effect by attenuating NLRP3 activity." (PMID 38343546, 2024). "Treatment with BSHX (0.25, 0.5, and 1 g/kg) significantly inhibited renal fibrosis and damage in 5/6 nephrectomized rats and simultaneously reduced oxidative stress and NLRP3 inflammasome activation." (PMID 38785272, 2024). "Future studies must explore the potential link of Mon effects on autophagy with NLRP3, ROS, IL-1β, and improvement in renal fibrosis to understand its renoprotective impact against DN better." (PMID 37498374, 2024). "TLYS has demonstrated the ability to ameliorate renal fibrosis by modulating NLRP3-mediated cell death, showcasing significant results after just two weeks of intervention in rat models." (PMID 39104818, 2024). "A subsequent study showed that HK-2 cells exposed to IL-1β strongly expressed TXNIP, NADPH oxidase 4 (Nox4), and ROS, indicating that inhibition of NLRP3 inflammasome activation suppresses renal fibrosis." (PMID 37500614, 2023). "Repression of NLRP3 inflammasome ameliorates renal fibrosis via a variety of mechanisms, such as improving endoplasmic reticulum stress and mitochondrial dysfunction and declining inflammation and oxidative stress." (PMID 37197172, 2023). "Recently, it was demonstrated that gemigliptin, a dipeptidyl peptidase-4 inhibitor, mitigated UUO-induced tubular atrophy and renal fibrosis in mice by downregulating NLRP3 activity." (PMID 37440209, 2023). "Another study demonstrated that the neutralization of IL-18, a downstream cytokine of the inflammasome-dependent pathway of NLRP3, can prevent renal fibrosis after UUO in mice." (PMID 37685978, 2023). "Our results also showed macrophage activation, NLRP3 activation, damaged renal tubular cells, and renal fibrosis due to UUO." (PMID 37685978, 2023). "This study aimed to explore the role of the HIF1α-BNIP3 pathway in mitophagy and the regulation of NLRP3 in renal fibrosis in UUO models by using BNIP3-knockout mice or NLRP3 inflammasome inhibitors." (PMID 36928344, 2023). "In brief, the NLRP3 inflammasome mediates inflammatory responses and participates in the early stage of renal fibrosis." (PMID 36928344, 2023). "Our previous research showed that MCC950, a specific inhibitor of the NLRP3 inflammasome, can attenuate cisplatin-induced renal fibrosis." (PMID 36928344, 2023).
renal fibrosis (continued). "In the present study, we found that the activation of the NLRP3 inflammasome and its downstream cytokines and renal fibrosis were increased at 7 days after UUO." (PMID 37685978, 2023). "Fucoidan, an active component in Laminaria japonica, attenuates renal fibrosis by inhibiting NLRP3-dependent pyroptosis in podocytes." (PMID 36815984, 2023). "In our study, there was more severe renal fibrosis, higher levels of mitochondrial ROS, and increased production of the NLRP3 inflammasome in BNIP3-KO mice following UUO." (PMID 36928344, 2023). "HIF1α-BNIP3-mediated mitophagy protected RTECs against hypoxia and renal tissue following UUO by decreasing mitochondrial ROS and inhibiting activation of the NLRP3 inflammasome to attenuate renal fibrosis." (PMID 36928344, 2023). "The deletion of BNIP3 decreased the activity of MnSOD, increased mitochondrial ROS and activated the NLRP3 inflammasome and renal fibrosis following UUO." (PMID 36928344, 2023). "Accumulating evidence supports the involvement of the NOD-like receptor family pyrin domain-containing protein 3 (NLRP3) inflammasome in driving renal fibrosis and inflammatory responses." (PMID 36421424, 2022). "More recently, we also proved that PT contributes to the prevention of renal fibrosis by attenuating NLRP3 inflammasome activation and inducing autophagy." (PMID 34983566, 2022). "Studies have found that in the Uox-knock-out-induced HUA and nephropathy rat line, the PI3K inhibitor 3-MA alleviates kidney injury accompanied by renal fibrosis, macrophage infiltration, and expression of NLRP3 and IL-1β in injured kidneys." (PMID 36438835, 2022). "The NLRP3 inflammasome not only amplifies renal inflammation but also promotes renal fibrosis, so NLRP3 inflammasome activation contributes significantly to the pathogenesis and progression of DN." (PMID 35910382, 2022). "The recent studies further suggested that RIPK3 is involved in the development of renal fibrosis, brain injury after subarachnoid hemorrhage, and lung injury by activating the NLRP3 inflammasome." (PMID 35514432, 2022). "A previous study showed that inhibition of NLRP3 reduced the expression of podocin and ameliorated renal fibrosis." (PMID 36204129, 2022). "The mechanisms by which hyperuricemia mediates NLRP3 inflammasome-induced kidney damage mainly include oxidative stress, endothelial dysfunction, inflammation, and renal fibrosis." (PMID 35382689, 2022). "Collectively, pteronene improved renal fibrosis by inhibiting the activation of NLRP3 inflammasome mediated by TGF-β and EMT by promoting autophagy." (PMID 34884572, 2021). "MCC950, a type of thiourea compound, is a specific inhibitor of NLRP3 and has been once administered to hypertensive kidney and renal fibrosis induced by oxalate crystallization animal models." (PMID 33783986, 2021). "We also found that farrerol alleviated inflammation and renal fibrosis by inhibiting p-NF-κB/NLRP3 and TGF-β/Smad signaling." (PMID 34858188, 2021). "UUO induced significant renal tubular necrosis and overexpression of RIP1-RIP3-MLKL axis proteins; these coincided with NLRP3 inflammasome activation, and subsequent development of renal fibrosis." (PMID 35069210, 2021). "Treatment with an autophagy inducer, pterostilbene, significantly reduced NLRP3 inflammasome activation and renal fibrosis after transforming growth factor beta (TGF-β) stimulation." (PMID 34443541, 2021). "Researchers have observed NLRP3′s role in renal fibrosis, diabetic nephropathy, obesity-related kidney disease, chronic glomerulonephritis, immunoglobulin A nephropathy (IgAN), crystal-related nephropathy, and hyperhomocysteinemia-induced renal injury." (PMID 33670423, 2021). "Inhibition of autophagy with the PI3K inhibitor 3-MA abrogated the development of kidney damage and attenuated renal fibrosis, macrophage infiltration, and expression of NLRP3 and IL-1β in injured kidneys." (PMID 33648977, 2021).
renal fibrosis (continued). "In accordance with our findings, a recent study also highlighted that the typical NLRP3 promotes the pathophysiology of various kidney diseases by mediating inflammation, and this is likely a critical priming mechanism for renal fibrosis." (PMID 34716316, 2021). "In a genetic murine CKD model, ablation of Nlrp3 results in attenuation of tubular injury and reductions in leukocyte infiltration and renal fibrosis." (PMID 34267672, 2021). "In UUO mice, the severity of renal fibrosis correlates with infiltration of M1 macrophages, which is related to the increase of NLRP3 expression and activation." (PMID 32660446, 2020). "Dihydroquercetin, phloretin, and icariin are all effective in ameliorating NLRP3 inflammasome-involved renal fibrosis." (PMID 33390969, 2020). "In unilateral ureteral obstruction (UUO)-induced renal fibrosis model, autophagy induction protected fibrosis through regulation of the expression of NLRP3, TGF-β, and IL-1β." (PMID 32582712, 2020). "Knock-out of Nlrp3 and Aim2 resulted in less injury, inflammation, and renal fibrosis after obstruction." (PMID 33117389, 2020). "The present study demonstrated that the NLRP3 inflammasomes mediate TGF-beta induced renal fibrosis." (PMID 32117956, 2020). "We also found that mitochondria-targeted antioxidant treatment has beneficial effects on mitochondrial dysfunction, Nlrp3 inflammatory body activation and renal fibrosis." (PMID 32979258, 2020). "In the UUO model, allopurinol reduced the renal content of soluble uric acid and inhibited NLRP3 activation, preventing the progression of proteinuria, as well as renal fibrosis and inflammation." (PMID 31649546, 2019). "NLRP3 was associated with TGF-β-induced epithelial-mesenchymal transition and renal fibrosis after unilateral ureteral obstruction (UUO)." (PMID 31694192, 2019). "Expression of NLRP3 inflammasomes, F4/80, inflammatory cytokine and renal fibrosis marker were measured using RT-PCR and Western blotting." (PMID 31796125, 2019). "Recent findings, however, indicate that NLRP3 and other inflammasomes are also involved in renal fibrosis." (PMID 32039201, 2019). "One of the interesting points of this study is the role of autophagy in activation of NLRP3 inflammasome signaling pathway during renal fibrosis." (PMID 30692509, 2019). "Excessive activation of NLRP3 inflammasome and down-regulation of Sirt1/Smad3 deacetylation pathway play a significant role in the evolution of renal fibrosis." (PMID 31118021, 2019). "In summary, this study provided new evidence for a better understanding of the biological activities of IL-22 in DN in terms of protection against renal fibrosis and NLRP3 inflammasome activation." (PMID 28726774, 2017). "Among the NLR family members (NLRP1, NLRP2, NLRP3, NLRP6, NLRP12, and NLRC4), NLRP3 deficient mice had less tubular injury, inflammation, and renal fibrosis in chronic kidney disease (CKD)." (PMID 29100270, 2017). "The results of the present study indicate that activation of the NLRP3 inflammasome accelerates renal fibrosis through mitochondrial dysfunction in the murine UUO model of CKD." (PMID 28348462, 2017). "Taken together, these findings suggested an important role for canonical NLRP3 inflammasome activation (the NLRP3 inflammasome-caspase 1-IL-1β/IL-18 axis) in renal fibrosis in the murine UUO model of CKD." (PMID 28348462, 2017). "For example, it has been shown that deletion of Nlrp3 protects renal fibrosis via inhibition of mitochondrial dysfunction." (PMID 27583382, 2016). "Together, it can thus be proposed that development of progressive renal fibrosis is primarily mediated via IL-18, while the role of upstream Nlrp3 is only minor." (PMID 24454932, 2014). "Here, we report a new role for NLRP3 in the pathogenesis of renal fibrosis." (PMID 42157945, 2026).